POSTN (periostin)
Diseases named in the same sentence as POSTN in open-access papers (continued):
Sharing a sentence is not in itself a finding about the gene and the disease.
Stroke (6 papers, 2018 to 2024). Sudden impairment of blood flow to a part of the brain due to occlusion or rupture of an artery to the brain. "We also investigated the associations of periostin levels and changes in periostin levels with stroke severity and short-term outcomes after IS." (PMID 30082879, 2018). "The increased periostin levels are associated with stroke severity." (PMID 30082879, 2018). "In conclusion, these findings suggest that the increase in serum periostin levels observed after stroke may be associated with the stroke severity in patients with LAA stroke." (PMID 30082879, 2018). "Accumulating evidence suggests that many types of MCPs, such as TNC, periostin, galectin-3, and osteopontin, contribute to aggravation or improvement of neuroinflammation in stroke at least partly by influencing the expression of each other." (PMID 33552066, 2020). "The aim of this study was to assess circulating periostin levels at different times after large-artery atherosclerotic (LAA) stroke and their association with stroke." (PMID 30082879, 2018). "Our results indicated that periostin levels increased significantly on day 6 after stroke, and this increasing trend persisted for at least 4 weeks after the event." (PMID 30082879, 2018). "Summarizing, initial periostin level may serve as a surrogate prognostic marker for hyperacute ischemic stroke reflecting stroke severity, long-term outcome, and patient’s eligibility for intervention." (PMID 36010292, 2022). "Additionally, we also find the relationship between systemic concentration of periostin measured in the acute phase of stroke and ASPECT score a valid assessment of the collateral circulation of the ischemic brain." (PMID 36010292, 2022). "TNC directly binds to other MCPs periostin and galectin-3, and may regulate the expression levels of each other in stroke, playing diverse roles." (PMID 33552066, 2020). "In this study, we investigated the post-stroke time course of serum periostin levels." (PMID 30082879, 2018). "Periostin as a prehospital point-of-care marker might have the potential to provide information about the prior collateral status and theexpected outcome, contributing to early diagnostics and the clinical decisionmaking of the stroke care team." (PMID 36010292, 2022). "Periostin kinetics could provide important information regarding the evolution of stroke." (PMID 36010292, 2022). "Serum periostin levels were measured using enzyme-linked immunosorbent assay on day 1 in 162 patients with LAA stroke and in 108 age- and sex-matched controls, on day 6 after stroke in 134 patients, and during the 4th week after stroke in 46 of the 162 patients." (PMID 30082879, 2018). "Second, this work lacked long-term clinical prognostic data and post-stroke cognition evaluations, which may be associated with serum periostin levels or the changes in periostin levels." (PMID 30082879, 2018). "In a binary logistic regression model, serum periostin level was a significant predictor for ASPECT < 6 status on admission, within 6 h after stroke onset (OR, 5.911; CI, 0.990–0.999; p = 0.015)." (PMID 36010292, 2022). "In this case‒control study, serum periostin and TNF-α levels were measured using ELISA, and patients were scored on the National Institutes of Health Stroke Scale (NIHSS) and modified Rankin Scale (mRS)." (PMID 36127647, 2022). "Our study aimed to determine the relationship between serum periostin levels, and the neutrophil–lymphocyte ratio (NLR) with ischemic stroke subtypes, clinical stroke scales, and acute prognosis in patients with acute ischemic stroke." (PMID 34137680, 2021). "In the current study, we aimed to determine the relationship between serum periostin levels and NLR with ischemic stroke subtypes, clinical stroke scales, and acute stage prognosis in patients with acute ischemic stroke." (PMID 34137680, 2021).
Stroke (continued). "First, our study demonstrated a direct correlation of the increase in periostin levels with NIHSS scores and stroke volume, while the correlation coefficients reflected weak or moderate correlation." (PMID 30082879, 2018). "Thus, circulating periostin levels may be associated with post-stroke cognitive impairment rather than the disability." (PMID 30082879, 2018). "However, our study included all stroke groups, and serum periostin levels were not correlated with acute prognosis." (PMID 34137680, 2021). "The increased periostin levels were positively correlated with the NIHSS scores and stroke volume but were not correlated with the mRS scores after adjusting for the NIHSS scores." (PMID 30082879, 2018). "In addition, the increase in periostin levels was positively correlated with the NIHSS scores and stroke volume, but not with the mRS scores after adjusting for the NIHSS scores." (PMID 30082879, 2018). "The increase in periostin levels observed during the first 6 days was correlated with National Institutes of Health Stroke Scale (NIHSS) scores on both day 1 (r = 0.219, p = 0.011) and day 6 (r = 0.291, p = 0.001), but not with stroke volume (r = −0.026, p = 0.771)." (PMID 30082879, 2018).
Ureteral obstruction (6 papers, 2015 to 2022). Obstruction of the flow of urine through the ureter. "In a mice model of unilateral ureteral obstruction, periostin was synthesized by the collecting duct cells and was associated with progression of renal lesions." (PMID 35331167, 2022). "Mice with genetic deletion of periostin showed substantially reduced inflammation and fibrosis in the models of unilateral ureteral obstruction (UUO) and nephrotoxic serum (NTS)-induced glomerulonephritis." (PMID 28536691, 2017). "Mice lacking the periostin gene show less interstitial inflammation as well as fibrosis preventing structural alterations in ureteral obstruction model." (PMID 35707463, 2022).
Airway obstruction (5 papers, 2020 to 2025). Obstruction of conducting airways of the lung. "This suggests potential for periostin to identify patients at risk of irreversible airway obstruction, a critical consideration given that current standard spirometry offers limited insight into ongoing fibrotic progression." (PMID 41374409, 2025). "Sputum periostin also reflects fixed airway obstruction more closely than serum periostin, probably due to the involvement of periostin in airway remodeling." (PMID 36763690, 2023). "Compared with other T2 biomarkers such as blood eosinophil count, induced sputum, or serum periostin, FeNO has some remarkable advantages, including its not invasive nature, easy repeatability, and possibility to be performed even in patients with severe airway obstruction." (PMID 36032508, 2022). "However, to our best knowledge, there have been no studies on the simultaneous assessment of periostin and TSLP levels and their potential link with the Th2 immune response in patients with these two obstructive lung diseases." (PMID 33203095, 2020).
atopic asthma (5 papers, 2014 to 2025). An asthma that is characterized by symptoms that are triggered by an allergic reaction caused by inhaled allergens such as dust mite allergen, pet dander, pollen and mold. "We found that periostin was strongly associated with atopic asthma, correlating significantly with exercise-induced bronchoconstriction, FeNO levels, and blood eosinophil counts, thereby indicating its role in Th2-driven inflammation and hyper-responsiveness." (PMID 39534447, 2024). "Periostin is linked to atopic asthma and correlates with exercise-induced bronchoconstriction, FeNO, and eosinophil counts, highlighting its role in Th2 inflammation." (PMID 39534447, 2024). "This supports our finding that periostin is more closely linked to atopic asthma, reflecting its specific association with Th2-driven inflammation." (PMID 39534447, 2024). "Periostin levels were significantly higher in the atopic asthma group than in the healthy control group (P = 0.003)." (PMID 39534447, 2024). "There are only isolated reports on the measurement of periostin in nasal secretions of patients with atopic asthma and nasal symptoms." (PMID 34796003, 2021). "Our study showed that both periostin and TSLP were associated with eosinophilic airway inflammation and seemed to be important drivers of atopic asthma pathobiology." (PMID 33203095, 2020). "Among them, IL-4 and IL-13-mediated severe atopic asthma with elevated serum IgE and periostin can be treated effectively with an anti-IgE monoclonal antibody, omalizumab, or an anti-IL-13 monoclonal antibody, lebrikizumab." (PMID 25359462, 2014). "Studying the presence of periostin in the nasal secretion of patients with atopic asthma and nasal symptoms is essential to determine the value of periostin as a non-invasive marker of type 2 allergic inflammation and the associated pathological remodeling of the airways." (PMID 34796003, 2021). "We may speculate that similar link between periostin and TSLP action occurs in atopic asthma, where periostin produced by MCs can affect epithelial cells via integrin binding activation, resulting in TSLP secretion." (PMID 33203095, 2020). "The results of our study show that periostin and TSLP are associated with eosinophilic airway inflammation and seem to be important drivers of atopic asthma but not COPD pathobiology." (PMID 33203095, 2020). "The aim of our study was to determine periostin and TSLP concentration in serum and induced sputum (IS) in patients with atopic asthma, chronic obstructive pulmonary disease (COPD), and controls, as well as to evaluate the potential link between periostin, TSLP, and Th2 immune response." (PMID 33203095, 2020). "The results of our study suggest that there might at least be local interplay between periostin and TSLP in airway inflammation in atopic asthma." (PMID 33203095, 2020).
autosomal dominant polycystic kidney disease (5 papers, 2012 to 2025). Autosomal dominant form of polycystic kidney disease. "In humans, periostin staining was observed in biopsies of glomerular diseases and within the cysts in autosomal dominant polycystic kidney disease." (PMID 22403621, 2012).
chronic obstructive pulmonary disease (5 papers, 2015 to 2025). A chronic and progressive lung disorder characterized by the loss of elasticity of the bronchial tree and the air sacs, destruction of the air sacs wall, thickening of the bronchial wall, and mucous accumulation in the bronchial tree. "Elevated periostin levels have been observed in patients with chronic airway diseases following fibrotic remodeling, including those with asthma and chronic obstructive pulmonary disease (COPD)." (PMID 39408746, 2024).
cutaneous melanoma (5 papers, 2007 to 2023). A primary melanoma arising from atypical melanocytes in the skin. "POSTN also accelerated human malignant cutaneous melanoma progression by modifying the melanoma microenviroment." (PMID 30867659, 2019). "Next, we investigated POSTN expression in 113 human cutaneous melanoma samples, including 46 primary lesions and 67 metastases." (PMID 18086302, 2007). "The selected candidate proteins in this study have been recently assessed in UM (i.e. OPN, MIA, CEACAM-1, MIC-1, and HSP27) and/or cutaneous melanoma as well as other cancers (i.e. SPON1 and POSTN) by either ELISA or immunohistochemistry or other techniques." (PMID 30867659, 2019).
dermatitis (5 papers, 2014 to 2024). An inflammatory process affecting the skin. "Furthermore, our study suggests that I3C mitigates AD-related skin inflammation by downregulating TSLP/periostin expression and inhibiting the signaling pathways associated with TSLP/periostin, including NF-κB and MAPK." (PMID 39722037, 2024). "Furthermore, periostin has been implicated in atopic conditions such as dermatitis and rhinitis/rhinosinusitis." (PMID 25981515, 2015). "In addition, periostin has been implicated in atopic conditions such as dermatitis and rhinitis/rhinosinusitis." (PMID 24146092, 2014). "Periostin was found to be involved in atopic conditions such as dermatitis, rhinitis/rhinosinusitis, allergic skin inflammations; and its upregulation was shown to induce extracellular matrix (ECM) tissue remodeling." (PMID 33195308, 2020). "In contrast, a sustained upregulation of periostin, such as due to a recurring stimulus, could drive remodeling beyond the physiologic adaption and perpetuate, by itself, the disease state (e.g., mice with chronic skin inflammation." (PMID 24146092, 2014). "Our investigation reveals the collaborative involvement of the MAPK/NF-κB and AhR pathways in DNCB-induced AD-like skin inflammation and barrier dysfunction orchestrated by TSLP and periostin, effects substantially mitigated by I3C treatment." (PMID 39722037, 2024). "In light of this, our study sought to investigate the therapeutic potential of targeting periostin and TSLP in AD-like skin inflammation." (PMID 39722037, 2024). "Moreover, regulation of FLS migration by POSTN and TWIST1 was confirmed in an in vivo animal model of skin inflammation." (PMID 25981515, 2015).
fibrous dysplasia (5 papers, 2010 to 2022). A genetic, non-inheritable disorder caused by osteoblastic differentiation defects that result in the replacement of bone marrow and trabecular bone by fibrous stroma and immature bone. "IHC and in situ hybridization were used to reveal a correlation between the expression of c-Fos/c-Jun and periostin in the fibrous component of human fibrous dysplasia lesions." (PMID 36224629, 2022). "Strong periostin expression was consistently noted in fibrous dysplasia and osteofibrous dysplasia, fibro-osseous bone tumours in which there is formation of woven bone with intramembranous ossification similar to that which occurs beneath the periosteum." (PMID 30202513, 2018). "There was strong staining for periostin in fibrous dysplasia and osteofibrous dysplasia, predominantly in the cellular fibrous stroma between bone trabeculae." (PMID 30202513, 2018). "These authors also analyzed POSTN levels in the sclerotic lesions developed in transgenic mice overexpressing c-fos, which are similar to those observed in fibrous dysplasia." (PMID 29946533, 2018). "Immunohistochemistry and in situ hybridization studies revealed that POSTN was expressed in the fibrous component of fibrous dysplasia lesions correlating with c-Fos expression." (PMID 29946533, 2018). "Also, periostin expression in the sclerotic lesions formed in transgenic mice overexpressing c-fos is similar to that found in fibrous dysplasia, in all lesion, transformed osteoblast expressed elevated periostin level, in contrast to normal osteoblasts." (PMID 36224629, 2022). "Moreover, mouse lacking periostin show defects like dwarfism and, periostin expression has been detected in fibrous dysplasia, a benign bone disease." (PMID 26809067, 2016).
glomerular diseases (5 papers, 2012 to 2022). "The scope of this review is to summarize the existing evidence that supports the role of periostin as a novel biomarker in glomerulopathies." (PMID 36551967, 2022). "Periostin was the most highly expressed matriceal protein in both animal models and in patients with glomerulopathies." (PMID 36551967, 2022). "A study aiming to describe expressed protein transcripts in patients with glomerular diseases identified periostin as the most expressed matricellular protein." (PMID 36551967, 2022). "Periostin staining was reported in areas of interstitial inflammation and fibrosis in the tubulointerstitium of patients with glomerular diseases (including MN) and kidney functional decline, independently of the type of glomerular disease." (PMID 36551967, 2022). "Also, increased glomerular periostin staining was related to low eGFR in different glomerulopathies." (PMID 34063373, 2021). "Periostin can activate integrin-linked kinase(ILK) and affect the survival, proliferation, differentiation and apoptosis of cells by binding to integrin α/β subunits, participating in the progression of glomerular diseases accompanied with proteinuria." (PMID 33241962, 2020).
idiopathic interstitial pneumonia (5 papers, 2014 to 2023). A class of diffuse lung diseases that typically affect the pulmonary interstitium, although some also have a component affecting the airways (for instance, Cryptogenic organizing pneumonitis). "We reported the upregulation of periostin in the lung tissues of mice with bleomycin-induced lung injury and its increased expression in the lungs and serum of human idiopathic interstitial pneumonias (IIPs)." (PMID 38002712, 2023). "Periostin, which reflects a poor prognosis of respiratory function in idiopathic interstitial pneumonia, is expected to be helpful as a biomarker reflecting disease activity and severity in routine medical care." (PMID 34439751, 2021).
interstitial lung disease (5 papers, 2021 to 2023). A diverse group of lung diseases that affect the lung parenchyma. "In chemotherapy-induced interstitial lung disease, increased POSTN expression is accompanied by neutrophil recruitment." (PMID 37958973, 2023). "Then, we summarise the pathological role of periostin in the development and progression of type 2 allergic inflammation and interstitial lung disease." (PMID 34439751, 2021).
intrahepatic cholangiocarcinoma (5 papers, 2018 to 2025). A carcinoma that arises from the intrahepatic bile duct epithelium in any site of the intrahepatic biliary tree. "In intrahepatic cholangiocarcinoma (ICC), tumor cells located at the leading edge exhibit high proliferative activity and are closely associated with stromal components, including endothelial cells and POSTN+ FAP+ fibroblasts." (PMID 41425545, 2025).
leukemia (5 papers, 2007 to 2024). A malignant (clonal) hematologic disorder, involving hematopoietic stem cells and characterized by the presence of primitive or atypical myeloid or lymphoid cells in the bone marrow and the blood. "In this regard, it has been recently demonstrated that within the B-ALL niche, MSCs produce increased levels of the matricellular protein, periostin (POSTN), impacting on leukemia progression." (PMID 35884364, 2022). "As demonstrated in a periostin knock-out leukemia mouse model, this molecular pathway resulted crucially involved in leukemia adhesion to MSCs, proliferation and dissemination." (PMID 33922612, 2021). "In tumors, leukemia and myeloma showed negligible levels of periostin expression whereas POSTN transcripts were detected in all solid tumors." (PMID 18086302, 2007). "Also, it was found that leukemia cell-derived CCL2 activates STAT3 to increase periostin expression in bone marrow-derived cells (BMDCs)." (PMID 36224629, 2022). "It is worth noting that POSTN knockout in a leukemia xenograft mouse model severely impaired leukemia cell proliferation and dissemination, suggesting that the analysis of leukemic ECM and its alterations could reveal new clinically relevant pharmacological targets." (PMID 35884364, 2022). "POSTN, in turn, increases the expression of CCL2 by leukemic cells and promotes leukemia cell proliferation and adhesion to BM-MSCs through the integrin-ILK-NF-κB signaling pathway." (PMID 35884364, 2022). "In line with the absence of POSTN expression in normal PBLs, periostin expression levels were negligible in hematological malignancies including leukemia (0.2 ± 0.2) and myeloma (1.5 ± 3.6)." (PMID 18086302, 2007).